THBS1 (thrombospondin 1)
Diseases named in the same sentence as THBS1 in open-access papers (continued):
Sharing a sentence is not in itself a finding about the gene and the disease.
tumor (continued). "On the other hand, MSCs can exert an anti-tumor effect by inducing tumor cell apoptosis, inhibiting cell proliferation, or secreting anti-angiogenic factors, such as thrombospondin-1 (TSP-1)." (PMID 41357241, 2025). "Elevated levels of THBS1 have been correlated with increased tumor aggressiveness and resistance to therapy, making it a potential therapeutic target." (PMID 41019041, 2025). "Thrombospondin 1 and 2, which regulate antitumor immunity and stimulate migration of tumor cells, were also upregulated exclusively by c-di-GMP+Pg LPS." (PMID 39669221, 2025). "THBSs support calcium-dependent cell attachment, and THBS1 is anti-angiogenetic and induces microvascular endothelial cell apoptosis, thus inhibiting tumor growth." (PMID 39696035, 2024). "THBS1, as a tumor suppressor gene, influences the growth of tumors by inhibiting angiogenesis and activating the transforming growth factor." (PMID 39075184, 2024). "They reported that thrombospondin 1 (which facilitates angiogenesis, tumor growth, and metastasis at the tumor site) expression was upregulated via FGF7-FGFR2b interaction through PI3K/Akt/mTOR signaling." (PMID 39766329, 2024). "The miR-17-92 cluster is upregulated in colon cancer and contributes to tumor development by promoting angiogenesis through the suppression of genes like thrombospondin 1 (TSP 1) and connective tissue growth factor (CTGF)." (PMID 38534736, 2024). "Increased PDAC aggressiveness was dependent on the tumor cell-mediated uptake of CAF-derived ANXA6-positive EVs carrying the ANXA6/LRP1/THBS1 complex." (PMID 38892190, 2024). "The tumor demonstrated a novel THBS1::ALK fusion containing Exons 1–7 of the thrombospondin 1 (THBS1) gene fused to Exon 19 of the anaplastic lymphoma kinase (ALK) gene via next-generation sequencing with the NextSeq sequencer." (PMID 39171208, 2024). "VT1021 is a cyclic peptide that induces the expression of thrombospondin-1 (TSP-1) in myeloid-derived suppressor cells (MDSCs) recruited to the tumor microenvironment (TME)." (PMID 38218979, 2024). "In the tumor microenvironment, TAN is induced to produce reactive oxygen species (ROS) and form neutrophil extracellular traps (NET), which can degrade thrombospondin-1 and promote tumor growth." (PMID 39132507, 2024). "ProclarixTM is a novel tumor marker developed for csPCa detection that incorporates the serum measurements of thrombospondin 1 (THBS1), cathepsin D (CTSD), total PSA, and percent free PSA, along with age." (PMID 38392564, 2024). "THBS1 facilitates tumour cell invasion and metastasis by enhancing epithelial‐mesenchymal transition." (PMID 38778448, 2024). "Tumor-associated macrophages express the signal-regulatory protein α (SIRPα) and the thrombospondin-1 which interact with the CD47 receptor, a don’t eat me signal, expressed by tumor cells and tumor-associated ECs." (PMID 38426109, 2024). "THBS1 promotes tumor progression and metastasis by regulating cell migration, proliferation, angiogenesis, and apoptosis." (PMID 38267974, 2024). "PEDF is generally considered a tumor suppressor, while for THBS1 and THBS2, controversial roles in cancer have been reported." (PMID 38339060, 2024). "THBS‐1 up‐regulated the invasiveness of HNC cells, but down‐regulated the invasiveness of tumor cells mediated by THBS‐1 when uPAR was inhibited." (PMID 38946720, 2024). "For instance, FN1 has been shown to be involved in cancer metastasis, while THBS1 regulates angiogenesis and tumor perfusion." (PMID 39593831, 2024). "THBS1 was notably upregulated in tumor tissues and A172 and U251 cells compared with that in normal tissues and NHA cells, respectively (P < 0.001)." (PMID 38267974, 2024). "Despite its simultaneous staining in the membrane and cytoplasm limiting its suitability as a theranostic marker, THBS1 is considered a potential therapeutic target due to its role in tumor progression and immune response." (PMID 39456895, 2024).
tumor (continued). "THBS1 promotes the progression and development of various cancers by regulating angiogenesis and tumor vascular perfusion." (PMID 39010084, 2024). "Taken together, these data indicate that THBS1 is a crucial matrix molecule that mediates tumor cell migration through interaction with adhesion receptor ITGAV." (PMID 39304722, 2024). "As depicted in UMAP plots, THBS2, THBS4 and COMP were primarily expressed by fibroblasts, while THBS3 was predominantly expressed by tumor cells and fibroblasts, and THBS1 was predominantly expressed by fibroblasts, monocyte-macrophages and endothelial cells." (PMID 38827236, 2024). "Since its identification as an angiogenesis inhibitor in 1990, THBS1 has attracted significant interest due to its role in tumor biology and potential as a therapeutic target." (PMID 39273281, 2024). "In our secretome analysis of TGFβ stimulated tumor cells, THBS1 was detected as one of the most abundant proteins." (PMID 39304722, 2024). "To inspect the clinical implications of cell communications between CAFs, macrophages, endothelial cells, and tumour cells, we detected expression associations between signature genes (FGF7/THBS1/MS4A4A/ZEB1) and tumour miRNAs." (PMID 38778448, 2024). "Our data extend the role of THBS1 and THBS2, which are not only able to hinder the vascular network and promote tumor-associated lymphangiogenesis but also exacerbate the malignant behavior of the iCCA cells." (PMID 38339060, 2024). "THBS1 is known for its involvement in angiogenesis and modulation of the extracellular matrix, reinforcing its role in promoting tumor growth and angiogenesis." (PMID 39456895, 2024). "THBS1 is highly expressed in breast cancer, oral squamous carcinoma, and lymphoma and enhances cancer progression by promoting tumor proliferation and metastasis." (PMID 38267974, 2024). "Although immunostaining and transcriptomic analyses demonstrated the localization of THBS1 in the tumor mesenchyme orthotopic tumors in Thbs1-/- mice showed low levels of THBS1." (PMID 37749092, 2023). "Within LFC-region samples, THBS1 expression primarily derives from a non-tumour astrocyte population." (PMID 37138086, 2023). "In this study, a subset of iCAFs that expresses high levels of the chemokine CCL2, known as ICAM1+ iCAFs, was identified and was found to recruit MDSCs (THBS1+ monocytes) to hypoxic tumor areas by binding to the receptor CCR2." (PMID 37743226, 2023). "Four of the top five most up-regulated glycoproteins in tumour ECM – thrombospondin-1 and -2, SPARC and peroxidasin – formed a connected subnetwork, pointing to their common functional roles in organising the collagen ECM and regulating cell–ECM adhesion." (PMID 37397358, 2023). "Our findings provide insights into the mechanism by which MO-MDSCs promote tumor progression via THBS1 production, particularly during metastasis." (PMID 37749092, 2023). "Of these, we selected the three genes with the highest transcript levels in 66cl4 CD45+ compared with CD45+ from 67NR tumours: Arg1, Fn1 and Thbs1." (PMID 37980483, 2023). "Dedieu’s group engineered a peptide, named TAX2, that targets the interaction between tumor-overexpressed thrombospondin-1 (TSP-1) and CD47." (PMID 37108657, 2023). "THBS1 provides strong survival ability, migration, and invasion of tumor cells by mediating excessive activation of the PI3K/AKT signaling pathway." (PMID 37686118, 2023). "EPCAM, PLAU and THBS1 were shown to be induced within TDLNs secondary to the afflux of tEV from primary tumor, and are involved in tumor cell recruitment and extra-cellular matrix remodeling." (PMID 38074683, 2023). "The anti-angiogenic effect of THBS1 is believed to contribute to tumor growth inhibition; however, the roles of THBS1 in carcinogenesis are multifaceted and contradictory." (PMID 37749092, 2023). "We found that 2.44% of all tumour cells expressed THBS1, and that HFC tumour cells expressed higher levels of THBS1 compared with LFC tumour cells." (PMID 37138086, 2023).
tumor (continued). "This study highlights the critical importance of bone marrow (BM)-derived monocyte lineages in enhancing tumor progression and provides evidence for the potential application of THBS1-targeted therapy as an effective treatment for aggressive CRC." (PMID 37749092, 2023). "According to earlier research, THBS1 is abundantly expressed in a variety of tumor types and encourages tumor cell adhesion, proliferation, apoptosis, invasion, and metastasis." (PMID 36991043, 2023). "The THBS1 expression levels were significantly higher in the metastatic nodules in lungs and tumor nodules in the abdominal cavity of the FN1 3′-UTR overexpressed group than that of the negative control group." (PMID 37771777, 2023). "In the present study, the expression of Thbs1, Tnfs, and Cd44 was down-regulated, indicating the potential tumor suppression function of the PEP1 peptide." (PMID 37446885, 2023). "In the tumor microenvironment, THBS1 has multifaceted roles in inhibiting angiogenesis and regulating antitumor immunity." (PMID 38203613, 2023). "The major monocyte population in both metastasis and primary tumor was Mon Thbs1; however, metastasis had increased Mon Fn1 fraction and reduction in antigen-presenting Mon MHC-II." (PMID 37756565, 2023). "We confirmed the decrease in THBS1 expression demonstrated in the RNA-seq data of G⍺12 KD tumors by qPCR on GSC23 tumor samples." (PMID 38104152, 2023). "In this study, ST revealed that THBS1 levels were higher in fibroblast-enriched tissues than in tumor tissues and NP tissues." (PMID 37124494, 2023). "FOLFOX treatment reduced primary tumor size in both WT and Thbs1-/- mice, but metastases were significantly suppressed in Thbs1-/- mice." (PMID 37749092, 2023). "We used the median THBS1 expression value as the cutoff value and explored the specific differences in tumor microenvironment immune cell infiltration between patients with low and high THBS1 expression." (PMID 36335208, 2022). "The same trend was also observed in colony formation assays, we found that knocking down THBS1 significantly facilitated tumor cells colony formation ability." (PMID 35354789, 2022). "Thrombospondin-1 (TSP-1) suppresses tumor progression via multiple mechanisms, including antiangiogenesis." (PMID 36505792, 2022). "Second, we have identified the biological function of THBS1 as a potential target to suppress tumor growth." (PMID 35354789, 2022). "(B, D) Quantification of the frequency of tumour regions expressing exclusively one probe or co-expressing two probes (yellow): Thbs1 only in red or Lgr5 only in green (B); Thbs1 only in red or Sca1 only in green (D)." (PMID 35543624, 2022). "In CTCL, CD47 is overexpressed in advanced MF and SS patients where it works in tandem with thrombospondin-1 to, not only allow for immune evasion, but also promote tumor cell migration and survival." (PMID 36059451, 2022). "At the molecular level, we provide evidence that the loss of miR-22 significantly affects the energetic metabolism and mitochondrial functions of hepatocytes, and the expression of tumor-promoting factors such as thrombospondin-1." (PMID 36139435, 2022). "The thrombospondin 1 (THBS1) acts within the tumour microenvironment to stimulate tumour cell motility, regulates antitumour immunity, inhibits angiogenesis, control tumour growth factors and extracellular proteases." (PMID 36354023, 2022). "THBS1 is a secreted protein that acts in the tumor microenvironment to regulate antitumor immunity, stimulate tumor cell migration, and regulate the activities of extracellular proteases and growth factors." (PMID 36276869, 2022). "TPST-1120 has demonstrated multiple modes of anti-tumor action in preclinical studies in advanced solid tumors, including an inhibition of tumor proliferation, an increase in the anti-angiogenic factor thrombospondin 1, and a reduction in T cell exhaustion." (PMID 36291769, 2022).
tumor (continued). "It was found to degrade the anti-cancer protein thrombospondin 1 in the pre-metastatic tumor microenvironment to promote cancer progression." (PMID 35269405, 2022). "Conversely, in THBS1 overexpressing mice, tumor growth is delayed or underdeveloped and capillaries in the tumor are constricted." (PMID 35409214, 2022). "THBS1 is an endogenous angiogenesis inhibitor that inhibits tumor growth by inhibiting tumor angiogenesis." (PMID 35409214, 2022). "A total of six upregulated genes (FN1, APOA1, CXCL8, MMP1, MMP3, and THBS1) in tumor tissue were identified by the differential analysis of 10 hub genes." (PMID 35719376, 2022). "Based on the results we report here, we propose a model for tumour initiation where mutant cells can ‘corrupt’ surrounding WT epithelial cells by secreting THBS1, leading to YAP activation in the receiving cells." (PMID 35543624, 2022). "Snail+ tumor cells produce thrombospondin-1 (TSP1) to promote tumor EMT in an autocrine manner, and indirectly through the generation of Treg-inducible regulatory DCs (DCreg)." (PMID 36211375, 2022). "sEVs derived from WERI RB1 cells were shown to promote tumor growth and mediate tumor deterioration in RB murine xenograft model via miR-92a, 20a, 129a, and 17, C-X-C chemokine receptor type 4, and thrombospondin-1." (PMID 36077715, 2022). "The bone marrow-derived Gr-1+ myeloid cells which express thrombospondin-1 suppress metastasis, and primary tumor-derived prosaposin play a key role in thrombospondin-1 induction in the Gr-1+ cells." (PMID 35780158, 2022). "Thrombospondin 1 (THBS1) was originally detected in thrombocytes, but it also shows expression in osteoblasts, macrophages, fibroblasts, and tumor cells." (PMID 35268340, 2022). "NET-associated NE and MMP9 cleave laminin and degrade thrombospondin-1 leading to the activation of integrin α3β1 and FAK/ERK/MLCK/YAP signaling, resulting in reactivation of dormant cancer cells during tumor metastasis." (PMID 35574410, 2022). "Lower THBS1 expression is reported to be associated with many kinds of cancers, indicating that THBS1 can serve as a tumor suppressor." (PMID 35354789, 2022). "We observed expression by tumor cells of thrombospondin (THBS1) and tissue inhibitors of metalloproteinases (TIMP1 and TIMP2), secreted factors involved in extracellular matrix remodeling." (PMID 36028490, 2022). "Constitutive deletion of Thbs1 in ApcMin/+ mice led to an increase in the number and aggressiveness of tumours, which was interpreted as a consequence of its anti-angiogenic role." (PMID 35543624, 2022). "The role of THBS1 as an antiangiogenic factor is well documented; however, its effect on tumor progression and metastasis remains controversial." (PMID 34268116, 2021). "Aberrant THBS1 methylation in tumor tissues was significantly higher than that in paracancerous normal tissues (p < 0.0001)." (PMID 34390026, 2021). "The average time of DFS was 25.1 months in 55 GC patients with THBS1 methylation and 35.1 months in 37 GC patients with THBS1 unmethylation in tumor tissues, indicating a significant difference (p < 0.01)." (PMID 34390026, 2021). "ApcMin/+:Thbs1−/− mice exhibited decreased survival and higher tumor multiplicities in the small and large intestine relative to ApcMin/+ mice when fed a low-fat Western diet." (PMID 33925464, 2021). "Originally discovered in platelets, THBS1 was then further characterized as a pluripotent effector involved in various regulons all disturbed in tumor cells." (PMID 35008641, 2021). "The high expression of THBS1 on T cells also suppressed angiogenesis and inhibited tumor development." (PMID 34095461, 2021). "Among many interactions, besides those of the integrins and signal regulatory protein α (SIRPα), CD47 binds thrombospondin-1, a potent gatekeeper of tumor progression." (PMID 34885092, 2021).
tumor (continued). "Through endogenous TGF-β1 activation, it has been shown that thrombospondin-1 (THBS1) up-regulates the PP system and promotes tumor cell invasion in MDA-MB-231 cells." (PMID 34680548, 2021). "THBS1 (also known as TSP1) is an endogenous anti-angiogenic factor that inhibits tumor development by suppressing angiogenesis." (PMID 34095461, 2021). "Multivariate survival analysis revealed an independent survival disadvantage in GC patients with THBS1 methylation in tumor tissue, PPLF, or serum specimens (p < 0.01)." (PMID 34390026, 2021). "Some studies have shown that THBS1 methylation is an early and frequent event in various tumors that can occur at each stage in the tumor and gradually increases as tumor progresses." (PMID 34390026, 2021). "THBS1 is a secreted glycoprotein involved in tumor progression via the regulation of ECM remodeling and angiogenesis." (PMID 34268116, 2021). "Some studies reveal that THBS1 promotes tumor cell invasion and metastasis in breast, gastric, and pancreatic cancers." (PMID 34390026, 2021). "It is plausible that the role of THBS1 in tumors depends on the cell-specific factors and signaling pathways that are activated in each specific tumor and contributes to optimize cell growth and survival." (PMID 35008641, 2021). "Conversely, thrombospondin-1 is a component of particles released by immune cells that mediate tumor cell killing." (PMID 33925464, 2021). "THBS1 is an important component of the extra-cellular matrix and has an important role in cancer development and regulating tumor cell behaviour." (PMID 34090482, 2021). "THBS1 is a large multidomain protein that interacts with many proteins, and can modulate tumor progression and metastasis." (PMID 34635636, 2021). "During the early stages of tumor growth, it was observed that platelet-derived thrombospondin 1 serves as a negative regulator of angiogenesis." (PMID 34099640, 2021). "VEGF and angiopoietin families secreted by tumor cells induce tumor angiogenesis, while anti-angiogenic factors, including thrombospondin-1 and angiostatin keep the tumor dormant." (PMID 33230600, 2021). "For example, THBS1 is mainly expressed in fibroblasts in the tumor stroma and there is better prognosis with activation of TGFβ-1 in CRC." (PMID 34502094, 2021). "In a murine model of prostate cancer metastasis to bone, increased TSP1 was observed in platelets, and implantation of tumors in Thbs1 null mice resulted in increased tumor size." (PMID 33925464, 2021). "THBS1 was the first member to be identified in the thrombospondins family and is a main player in the tumor microenvironment." (PMID 33912465, 2021). "Other studies have shown CD36 to be anti-angiogenic via thrombospondin-1 signaling, leading to apoptosis in normal EC, or by blocking the vascular endothelial growth factor receptor 2 pathway in tumor EC." (PMID 34888367, 2021). "Another example of matrix being able to modulate the orientation of tumor immunity one way or another is thrombospondin-1." (PMID 33718177, 2021). "Thrombospondin 1 (THBS1) is known to play a key role in tumor metastasis, and aberrant DNA methylation is one of the mechanisms regulating THBS1." (PMID 34390026, 2021). "TAX2 is a cyclic peptide targeting tumor-overexpressed thrombospondin-1 (TSP-1) to prevent CD47 receptor activation." (PMID 34638503, 2021). "The status of THBS1 methylation was detected by quantitative methylation‐specific PCR (MSP) in tumor tissues, paired PPLF, and serum from 92 GC patients." (PMID 34390026, 2021). "Our previous studies demonstrated that shRNA against Ido1, Foxo3, Thbs1, and Clec4a2 can enhance the antitumor effect of Her2/neu DNA vaccine in the murine tumor model." (PMID 32933162, 2020).